MIR6862-2 (microRNA 6862-2)
Synonyms: hsa-mir-6862-2
Gene: MicroRNA gene on chromosome 16 (28,724,252 to 28,724,321, forward strand). Ensembl gene ENSG00000278340.
Homologues: Paralogues in human: MIR6862-1 (100% identical).